CRP (C-reactive protein)
Diseases named in the same sentence as CRP in open-access papers (continued):
Sharing a sentence is not in itself a finding about the gene and the disease.
pancreatic adenocarcinoma (7 papers, 2015 to 2025). "Multivariate logistic analysis has shown that parameters independently associated with primary pancreatic adenocarcinoma were CRP > 10 mg/dL (p = 0.012), CA 19-9 > 230 U/mL (p = 0.043), and diameter of the Wirsung > 3 mm (p = 0.005)." (PMID 33430887, 2021). "Univariate analysis identified 5 parameters as diagnostic for primary pancreatic adenocarcinoma (PDAC), including modified Glasgow Prognostic Score > 1, CRP > 10 mg/dL, Wirsung duct > 3 mm, CA 19-9 > 230 U/mL, and albuminemia < 35 g/L." (PMID 33430887, 2021). "Initial comparison of recruited individuals revealed significantly higher CA19.9 and C-reactive protein (CRP) levels in patients with pancreatic adenocarcinoma when compared to healthy controls." (PMID 26266370, 2015). "The association between high CRP to PDAC remains innovative: in fact, this inflammatory marker has been associated with poor survival after resection and with low resectability rate but never with histologic origin (primary pancreatic adenocarcinoma, PDAC)." (PMID 33430887, 2021).
panniculitis (7 papers, 2020 to 2025). Inflammation of the subcutaneous adipose tissue. "Systematic examination in another medical center was otherwise unrevealing except for increased ESR/CRP and “mesenteric panniculitis” indicated by abdominal CT." (PMID 35547205, 2022). "Although in our study, patients with panniculitis had higher white blood cell and CRP levels." (PMID 33141504, 2021). "The increase of serum white blood cell level and CRP level can predict the diagnosis of panniculitis, but it is not completely accurate." (PMID 33141504, 2021).
pelvic inflammatory disease (7 papers, 2018 to 2025). Pelvic inflammatory disease (PID) is an acute or chronic inflammation in the pelvic cavity. "The C-reactive protein level and intensity of pain in women with pelvic inflammatory diseases significantly decreased after BV gel was topically applied with an ultrasound device and doxycycline was administered." (PMID 32872552, 2020).
penile cancer (7 papers, 2013 to 2023). A primary or metastatic malignant neoplasm that affects the penis. "A high preoperative serum CRP level was associated with poor survival in patients with penile cancer." (PMID 23642165, 2013). "In a recently published study we were able to show that a high preoperative serum CRP level was associated with poor survival in patients with penile cancer." (PMID 24148787, 2013). "The nodal status is a strong predictor for cancer specific death in patients with penile carcinoma, and the C-reactive protein (CRP) level at diagnosis has recently been shown to be associated with poor clinical outcome in various solid malignancies." (PMID 24148787, 2013). "In addition, a high pre-treatment CRP value greater than 15 mg/L was associated with advanced staging, greater metastatic spread and a poorer 5-year survival outcome in penile cancer." (PMID 32705478, 2020). "High levels of circulating CRP have recently been associated with metastatic disease and a poor prognosis in various malignancies, including renal cell carcinoma, urothelial carcinoma, castration-resistant prostate cancer, and even penile cancer." (PMID 24148787, 2013). "In addition, this study shows that elevated CRP levels are associated with higher tumor stages and nodal disease, the most important prognostic factors for penile carcinoma." (PMID 24148787, 2013). "The aim of this retrospective two-center study was to evaluate the impact of CRP levels at diagnoses on the prognosis of penile cancer patients." (PMID 23642165, 2013). "In conclusion, we have shown that a high preoperative serum CRP level is closely correlated with nodal disease and could help identify patients with penile cancer who may profit from inguinal lymph node dissection." (PMID 24148787, 2013). "This retrospective analysis included 79 penile cancer patients with information about their serum CRP value prior to surgery who underwent either radical or partial penectomy at two German high-volume centers (Ulm University Medical Center and Hannover Medical School) between 1990 and 2010." (PMID 23642165, 2013). "This study shows for the first time that elevated preoperative CRP levels are also associated with penile cancer stage, but not grade." (PMID 23642165, 2013). "Since a high preoperative serum CRP level was closely correlated with nodal disease, it could be used as an additional marker to help identify patients with penile cancer who may benefit from inguinal lymph node dissection." (PMID 24148787, 2013). "Moreover, the CRP level correlated significantly with the tumor stage: 73.7% of all patients with CRP >15 and 36.7% of those with CRP ≤15 mg/l suffered from locally advanced (pT≥2) penile cancer (p<0.007, Fisher’s exact test)." (PMID 23642165, 2013). "However, focusing on the subgroup of patients without metastasis, both advanced local tumor stage (≥pT2; HR 8.78, 95% CI 1.1-70.7, p=0.041) and an elevated CRP value (>15 mg/l; HR 3.34, 95% CI 1.04-10.7, p=0.043) were identified as predictors of poor clinical outcome in patients with penile cancer." (PMID 23642165, 2013). "Moreover, we had only limited information about potential superinfections of the penile cancer which might have influenced the preoperative CRP value." (PMID 23642165, 2013). "This clearly indicates that the tumor itself seems to be involved in the elevation of serum CRP levels and that the phenomenon of elevated CRP in penile cancer is not simply a consequence of superinfection." (PMID 24148787, 2013).
Peri-Implantitis (7 papers, 2023 to 2025). An inflammatory process with loss of supporting bone in the tissues surrounding functioning DENTAL IMPLANTS. "There is also a statistically significant risk of peri-implantitis in obese patients because of higher C-reactive protein and MMP-8 levels in the serum and PICF." (PMID 37232785, 2023). "Most studies focused on peri-implantitis and evaluated serological markers such as C-reactive protein and cytokines (IL-6, IL-1β, IL-17, tumour necrosis factor-α), along with haematological parameters including neutrophils, haemoglobin, platelets, and lymphocytes." (PMID 41301163, 2025). "In a case–control study with 100 participants, the authors found that serum CRP was significantly higher in patients with peri-implantitis (mean 0.615 mg/dL) compared to systemically healthy controls (mean 0.201 mg/dL), based on fasting morning venous samples analysed by latex-enhanced nephelometry." (PMID 41301163, 2025). "While CRP is known as a marker for systemic inflammation, it has also been detected in PICF at peri-implantitis sites." (PMID 36565371, 2023).
pheochromocytoma (7 papers, 2019 to 2025). "In IL-6-secreting pheochromocytomas, extreme CRP and fibrinogen levels have been observed alongside very high ESRs (ESR > 100 mm/hour)." (PMID 41357012, 2025). "Administering doxazosin lowered the CRP and IL-6 levels, then IL-6-producing pheochromocytoma was suspected, and adrenalectomy was performed." (PMID 37908215, 2023). "Although little is known on the topic, at least one study has already described hepatic cytolysis with elevated transaminases and C-reactive protein (CRP) in a patient suffering from pheochromocytoma." (PMID 35326472, 2022). "Furthermore, other studies have found that not only CBC parameters but also acute-phase proteins, such as elevated C-reactive protein, were higher in patients with pheochromocytoma than healthy subjects or patients with other types of hypertensive conditions." (PMID 38655872, 2025).
primary biliary cholangitis (7 papers, 2009 to 2026). Primary biliary cholangitis (PBC) is a chronic and slowly progressive cholestatic liver disease of autoimmune etiology characterized by injury of the intrahepatic bile ducts that may eventually lead to liver failure. "Later, Bell and colleagues reported a high frequency of autoantibodies against a certain dissociated and tissue-bound form of CRP, recognized as monomeric CRP (mCRP) in SLE, and at lower prevalence rates in subacute cutaneous lupus erythematosus and primary biliary cirrhosis." (PMID 20003354, 2009).
Psoas abscess (7 papers, 2018 to 2026). Abscess of the PSOAS MUSCLES resulting usually from disease of the lumbar vertebrae, with the pus descending into the muscle sheath. "Five predictor variables were screened by LASSO regression and plotted as a nomogram, including ALB, CRP normalization days, Bone graft materials, Psoas abscess, Jumping lesions." (PMID 42052375, 2026). "Although ESR and CRP were abnormal in some of them postoperation immediately, because of surgical trauma and the psoas abscess still existing for a period of time, both of them returned to normal levels at the final follow-up." (PMID 33579244, 2021). "However, initial investigations revealing a markedly high C-reactive protein (CRP) concentration prompted further computed tomography (CT) imaging of her abdomen and pelvis, which uncovered an iliopsoas abscess presumably stemming from antecedent trauma." (PMID 39020267, 2024). "Laboratory testing and physical examinations indicated that CRP (13.3 ± 11.0 vs. 9.4 ± 8.4 mg/dL, p = 0.02), LDH (290 ± 153 vs. 239 ± 88 IU/L, p = 0.02), BUN (32.0 ± 32.0 vs. 20.9 ± 10.6 mg/dL, p = 0.007), and Cr (1.7 ± 2.5 vs. 1.0 ± 0.8 mg/dL, p = 0.02) were higher in psoas abscess cases." (PMID 30486831, 2018).
psoriasis vulgaris (7 papers, 2013 to 2024). Plaque psoriasis is the most common presentation of psoriasis. "Patients with pustular psoriasis have significant elevated hs-CRP compared with that of plaque psoriasis patients." (PMID 31275060, 2019). "As for the technological restriction, only a few psoriasis vulgaris patients showed serum CRP, IL-6 and TNF-α detected previously, so most patients could not be included in this retrospective cohort." (PMID 39335643, 2024). "Thus, we established a simple score scale composed of serum CRP, IL-6 and TNF-α levels to estimate the risk for progressing to PsA among psoriasis vulgaris patients, and validated the scale internally and for a retrospective cohort." (PMID 39335643, 2024). "The objective was to measure serum adipokines in patients with plaque psoriasis, and serum levels of chemerin, resistin, and CRP were significantly higher in patients with chronic plaque psoriasis compared with controls independent of age, sex, BMI, and metabolic comorbidities." (PMID 31275060, 2019). "In this study, the cross-sectional study identified the fact that serum CRP, IL-2, IL-6, TNF-α and IFN-γ levels were significantly increased in PsA patients, and positive serum CRP, IL-6 and TNF-α were independently associated with PsA among psoriasis vulgaris patients." (PMID 39335643, 2024). "The simple score, composed of CRP, IL-6 and TNF-α, with the cut-off value of 1.8, also showed satisfying predictive performance for PsA among the retrospective cohort of psoriasis vulgaris patients externally (AUC = 0.686, p = 0.010, sensitivity = 59.1%, specificity = 78.1%)." (PMID 39335643, 2024). "The second subject is a 45 y/o male patient with a clinical diagnosis of psoriasis vulgaris, tested rheumatoid factor negative, CRP 0.8 mg/L, with no signs of erosion (X-ray analysis)." (PMID 35892489, 2022). "We conducted a cross-sectional study to compare the levels of serum inflammatory indicators between psoriasis vulgaris patients who progressed to PsA and those who did not, and found that CRP, IL6 and TNF-α levels were all higher in PsA patients than in controls." (PMID 39335643, 2024). "In the retrospective cohort, the previous results of serum CRP, IL-6, and TNF-α detection were collected for the included psoriasis vulgaris patients who did not progress into PsA, and the clinical prognosis was followed up for at least 4 years." (PMID 39335643, 2024).
resistant hypertension (7 papers, 2016 to 2025). "CRP was also found to be associated with LV hypertrophy in a cross-sectional study consisting of 705 patients with resistant hypertension." (PMID 41141372, 2025). "It was previously reported that in patients with resistant hypertension, plasma level of inflammatory cytokine such as C-reactive protein (CRP) was considerably elevated, and the underlying mechanisms operating in these processes are not fully investigated yet." (PMID 26801405, 2016). "Coincidently, SLE patients have significantly higher risks of resistant hypertension compared to non-SLE patients and this resistant hypertension is associated with lower renal function, and increased circulation inflammatory markers (erythrocyte sedimentation rate and C-reactive protein)." (PMID 35770194, 2022).
rheumatic heart disease (7 papers, 2014 to 2023). An autoinflammatory condition following an infection with Group A Beta Hemolytic Streptococcus (GABHS), in which the heart is attacked by antibodies formed in reaction to a recent GABHS infection. "So, we sought to study the effect of LAP on the inflammatory markers, CRP and IL-6, in patients with chronic rheumatic heart disease." (PMID 33638745, 2021). "In addition to rheumatic carditis, six patients had two minor manifestations (CRP ≥3.0 mg/dL + fever in three patients; and CRP ≥3.0 mg/dL + monoarthralgia in three patients)." (PMID 34179142, 2021). "The highly sensitive C-reactive protein may increase in chronic rheumatic heart disease, indicating that an inflammatory response still persists in the chronic phase." (PMID 25478552, 2014). "C-reactive protein and interleukin-6 mean levels were significantly higher in patients with rheumatic heart disease not taking long-acting penicillin compared to patients with rheumatic heart disease taking long-acting penicillin and to the control group." (PMID 33638745, 2021).
Rickettsiosis (7 papers, 2015 to 2025). A group of infectious diseases that is caused by Rickettsia. "C-reactive protein (CRP) levels, a marker commonly associated with rickettsial infections, consistent with findings from previous studies, were significantly higher in the rickettsiosis group." (PMID 40094918, 2025). "The elevated CRP levels in rickettsiosis likely reflect its acute nature, prompting rapid testing due to fast onset and inflammation." (PMID 40094918, 2025). "Elevation of CRP was found in some studies of rickettsioses, but the values of PCT were rarely been mentioned." (PMID 32398008, 2020). "We found that only 10.8% of patients with rickettsioses had a CRP value > 150 mg/L and only 14.2% of that had a PCT value > 2.0 ng/mL in the acute phase." (PMID 32398008, 2020). "In Rickettsia infection, a high level of CRP was detected, but WBC count showed a slight elevation." (PMID 33322277, 2020). "The aim of this study was to investigate the changes of CRP and PCT values in acute and convalescent phases of rickettsioses and the association of these two markers with other biochemistry markers and with the response to doxycycline treatment in patients with rickettsioses." (PMID 32398008, 2020). "In febrile patients with markedly high CRP (> 150 mg/L) or PCT values (> 2.0 ng/mL), other infectious etiologies other than rickettsioses alone should be considered." (PMID 32398008, 2020). "Although C-reactive protein (CRP) and procalcitonin (PCT) are widely used inflammatory markers for infectious diseases, their role and potential application for rickettsioses were rarely studied." (PMID 32398008, 2020). "Only 10.8% of patients had CRP levels > 150 mg/L and only 14.2% of patients had PCT levels > 2.0 ng/mL in the acute phase of three rickettsioses." (PMID 32398008, 2020). "Results of this study revealed changes of CRP and PCT values in the acute and convalescent phases of rickettsioses, which might reflect the progression and regression of disease." (PMID 32398008, 2020). "This implied that for febrile patients presenting with CRP values higher than 150 mg/L or PCT values higher than 2.0 ng/mL, the diagnosis of rickettsioses might be less likely; other bacterial infections should be put in the list of differential diagnosis." (PMID 32398008, 2020). "Several previous studies had shown CRP and PCT values reflected disease severity of rickettsioses." (PMID 32398008, 2020). "The findings suggested both CRP and PCT values may reflect disease progression in rickettsioses as well as other common bacterial infections." (PMID 32398008, 2020). "This is a study aimed at the specificity of CRP and PCT values in three rickettsial diseases." (PMID 32398008, 2020). "CRP and PCT values might be useful in clinical investigations for patients with suspected rickettsioses and in predicting the response to doxycycline treatment for rickettsioses." (PMID 32398008, 2020). "In addition, the trend of CRP and PCT values, their correlation with other clinical biomarkers, and whether CRP and PCT values could be predictors of treatment response in rickettsioses were not well understood." (PMID 32398008, 2020). "However, there was no systemic investigation on CRP and PCT values in rickettsioses yet." (PMID 32398008, 2020).
schistosomiasis (7 papers, 2013 to 2024). An infectious disease caused by parasitic trematodes of the genus Schistosoma that colonize human blood vessels and release eggs that can cause granulomatous reactions leading to acute (swimmer's itch or acute schistosomiasis syndrome) or chronic disease. "We believe that this study is the first to report the prognostic significance of TILs and CRP in schistosomiasis-associated CRC patients." (PMID 37277702, 2023). "Wami, evaluated the role of resistin and CRP in schistosomiasis in children 1–10 years old and CRP was observed to be one of the inflammatory biomarkers in children with schistosomiasis." (PMID 31856765, 2019). "Interestingly, in rats, treatment of platelets with CRP bestowed significant protection capacity against schistosomiasis in transfer experiments and obviously participated in the natural resistance of this species to schistosomal infection." (PMID 35402541, 2022). "In a prospective cohort study, HIV-infected patients from helminth endemic areas underwent clinical assessment and blood draw for schistosomiasis and strongyloides serology, routine haematology and inflammatory markers (ESR and CRP)." (PMID 24010677, 2013). "STH infection was a significant negative predictor of IgG1 galactosylation, and schistosomiasis and CRP level near-significant predictors." (PMID 27306703, 2016). "However, the prognostic value of intratumor CRP remains unknown, especially in CRC patients with schistosomiasis." (PMID 37277702, 2023).
Sciatica (7 papers, 2014 to 2026). Pain in the lower back and hip radiating in the distribution of the sciatic nerve. "Markers for inflammation (high serum C-reactive protein levels) were potentially associated with sciatica in 1 study." (PMID 29856783, 2018). "C-reactive protein (CRP), as an indicator of inflammation, has been reported to be elevated in the serum of sciatica patients." (PMID 34925462, 2021). "To facilitate the diagnosis of sciatica by clinicians using the selected DEIRGs (RLN1, EREG, FAM19A4, WFIKKN1, and CRP), we constructed a nomogram model." (PMID 34925462, 2021). "AZU1, BPI, TCF7L2, and WFIKKN1 were upregulated in sciatica patients, while ANGPTL4, CRP, EREG, FAM19A4, FGF1, LOC100129216, PLXNB1, RLN1, and RXFP2 were downregulated." (PMID 34925462, 2021). "Previous studies have reported serum inflammatory biomarkers of sciatica, and these include TNF-α, IL-4, IL-6, IL-8, IL-10, IL-17, IL-21, T helper lymphocytes 17, phospholipase A2, C-reactive protein, C-X3-C motif ligand 1, C-C motif ligand 2 and mast cell proteinase-1." (PMID 33535986, 2021).